HPS1 (HPS1 biogenesis of lysosomal organelles complex 3 subunit 1)
Diseases named in the same sentence as HPS1 in open-access papers (continued):
Sharing a sentence is not in itself a finding about the gene and the disease.
melanoma (1 paper, 2017). A malignant, usually aggressive tumor composed of atypical, neoplastic melanocytes. "Silencing of the BLOC-3 subunits Hps1 and Hps4 results in the mislocalization of Rab32 and Rab38 and a reduction in pigmentation in a melanoma cell line." (PMID 28438206, 2017).
Obesity (1 paper, 2019). Accumulation of substantial excess body fat. "However other co-morbidities present in this case, such as obesity, are also associated with hyperfiltration of the glomerulus, leading to FSGS21–23, so a causal relationship between mutations in HPS1 and an increased susceptibility to developing FSGS is difficult to establish from this case." (PMID 31776394, 2019).
reovirus infection (1 paper, 2022). "No induction of MLKL phosphorylation was observed in hPS1 fibroblast upon reovirus infection or stimulation with the necroptosis-inducing mixture TBZ." (PMID 35869278, 2022). "Overexpression of JAM-A in the JAM-A negative PSC line hPS1, naturally resistant to reovirus-induced cell death, led to strongly increased cell death induced by reovirus infection and already resulted in productive infection, indicated by σ3 expression, at low MOI." (PMID 35869278, 2022).
infection (4 papers, 2012 to 2022). The state of being infected such as from the introduction of a foreign agent such as serum, vaccine, antigenic substance or organism. "Within the Qivr19 interval, only one gene, Hps1 (Hermansky-Pudlak syndrome 1 homolog (human)), has been associated with the host responses to infection." (PMID 22905720, 2012). "At 24 hours post-infection, there is a population representing 1.34% of the HPS-1-depleted cells containing higher loads of intracellular bacteria, while this population only represents 0.4% of the control cells." (PMID 33898333, 2021). "Additionally, MHC binding and cytokine activity were enhanced pathways in HPS1 patient macrophages following infection, while oxidative phosphorylation remained dampened." (PMID 36302964, 2022).
HPS1 also shares sentences with these, for which no sentence is quoted: oculocutaneous albinism (3 papers); idiopathic pulmonary fibrosis (2); bronchiectasis (1); Chediak-Higashi syndrome (1); fibrosis (1); Griscelli syndrome (1); Hermansky-Pudlak Syndrome-1 (1); liver cancer (1); Menkes syndrome (1); Menorrhagia (1); neutropenia (1); oculocutaneous albinism type 1 (1); pericardial effusion (1); respiratory failure (1); restrictive lung disease (1); upper respiratory tract infections (1).